IL1B (interleukin 1 beta)
Diseases named in the same sentence as IL1B in open-access papers (continued):
Sharing a sentence is not in itself a finding about the gene and the disease.
familial Mediterranean fever (63 papers, 2009 to 2025). Familial Mediterranean fever (FMF) is an autoinflammatory disorder characterized by recurrent short episodes of fever and serositis resulting in pain in the abdomen, chest, joints and muscles. "Pyroptosis has recently been shown to be the critical mechanism of IL‐1β‐mediated systemic pathology in the autoinflammatory disease Familial Mediterranean Fever (FMF), which is caused by missense mutations in Mefv that activates the pyrin inflammasome." (PMID 31015277, 2019). "The prototypic SAID is familial Mediterranean fever (FMF), an autosomal recessive disease caused by mutations in the MEFV gene that result in overactivity of the pyrin inflammasome and interleukin (IL)‐1β secretion, which presents with episodic serositis." (PMID 35658515, 2022). "Familial Mediterranean fever is an autoinflammatory disease in which large amounts of IL-1β-bearing NETs are released during attacks, and the NETs further amplify IL-1β production by peripheral blood mononuclear cells." (PMID 36175465, 2022). "Familial Mediterranean fever (FMF) is a disease that is characterized by spontaneous episodes of activation of specific inflammatory pathways, including inflammasomes, causing IL-1B release and chronic inflammation, which drive AA amyloidosis and CKD." (PMID 35743929, 2022). "Colchicine, a low-cost anti-inflammatory agent that is widely used in pericarditis, gout, and familial Mediterranean fever, and has been shown to suppress the production of IL-1β, IL-6, and IL-18." (PMID 36555579, 2022). "It is intriguing that Brucella downregulates macrophage MEFV expression, the gene responsible for familial Mediterranean fever, the prototype IL-1β-mediated autoinflammatory disease." (PMID 35979363, 2022). "Conflicting reports exist on the number of NK cells in patients with familial mediterranean fever (FMF, mutation in MEFV, resulting in abnormal regulation of IL-1β activation)." (PMID 32010140, 2019). "For example, IL-1β-bearing NETs characterize inflammatory flares of typical autoinflammatory diseases such familial Mediterranean fever (FMF) and Still’s disease." (PMID 30234114, 2018). "Familial Mediterranean fever is an IL-1β dependent auto-inflammatory disease and is related to dysregulation of nod-like receptor family pyrin domain-containing 3 inflammasome (NLRP3)." (PMID 25887962, 2015). "Roles of type I IFNs have also been shown in familial Mediterranean fever, an autoinflammatory syndrome associated with NLRP3 dysregulation and aberrant IL-1β secretion." (PMID 25486008, 2014). "A functional link between IL-1β and IL-6 is also suggested by the observation that patients with familial Mediterranean fever (FMF), an auto-inflammatory disease, were successfully treated with TCZ." (PMID 25271853, 2014). "The familial Mediterranean fever (FMF) gene (MEFV) encodes pyrin, a major regulator of the inflammasome platform controlling caspase-1 activation and IL-1β processing." (PMID 19784369, 2009). "Autoinflammatory diseases, such as tumor necrosis factor receptor‐associated periodic syndrome (TRAPS) and familial mediterranean fever (FMF), have all been directly linked with excessive production of IL‐1β and IL‐18,14 because of heightened inflammasome responses." (PMID 35832835, 2022). "In 2009, the FDA approved canakinumab, a human monoclonal antibody that specifically and selectively targets IL-1β, for treating periodic fever syndromes, including familial Mediterranean fever (FMF), CAPS, and Still’s disease." (PMID 40371323, 2025). "Canakinumab is a human anti-IL-1β monoclonal antibody, and clinically used for FCAS, MWS, CAPS, familial Mediterranean fever (FMF), mevalonate kinase deficiency (MKD), tumor necrosis factor receptor-associated periodic syndrome (TRAPS), and AOSD." (PMID 37881433, 2023).
familial Mediterranean fever (continued). "Active caspase 1 is crucial for the proteolytic activation of Interleukin (IL)-1β, which acts as the major cytokine in multisystem autoinflammatory disorders such as Familial Mediterranean Fever (FMF)." (PMID 36009585, 2022). "Colchicine, known for its use in gout, Familial Mediterranean Fever (FMF), and other IL-1β mediated syndromes, has many anti-inflammatory and cardiovascular protective properties." (PMID 33593369, 2021). "These factors were IL-1β, prostaglandin-endoperoxide synthase 2 (PTGS2/COX-2), NOD-like receptor family CARD domain-containing protein 4 (NLRC4), Familial Mediterranean Fever (MEFV) gene, and caspase 5 (CASP5)." (PMID 40861543, 2025). "Finally, the IL-1β inhibitors anakinra and canakinumab have proven marked efficiency in treatment of renal amyloidosis in patients with Familial Mediterranean Fever (FMF)." (PMID 40486517, 2025). "In familial Mediterranean fever (FMF), knock-in macrophages expressing chimeric Mefv (V726A) pyrin exhibit pyroptosis and GSDMD-mediated IL-1β secretion upon infection with Clostridium difficile." (PMID 39994107, 2025). "Several SAIDs, including familial Mediterranean fever (FMF), are mediated by excessive interleukin (IL)-1β production." (PMID 37714974, 2023). "Hereditary mutations in pyrin, the causative for Familial Mediterranean fever (FMF) and in PSTPIP1, a pyrin interacting protein responsible for Pyogenic arthritis, pyoderma gangrenosum, and acne syndrome (PAPA), are responsible for impaired regulation of IL-1β maturation." (PMID 20482797, 2010). "Interestingly, in Familial Mediterranean Fever patients, circulating levels of IL-1β are not correlated to the severity of the disease, however, they respond highly to IL-1β blockade therapy, indicating its fundamental role in the orchestration of the disease." (PMID 40547021, 2025). "Conversely, neutrophils from patients with familial Mediterranean fever (FMF) and AOSD released IL-1β bearing NETs during disease attacks." (PMID 33240258, 2020).
pancreatitis (63 papers, 2006 to 2026). Inflammation of the pancreas. "Compared to macrophages from the control pancreas, macrophages from the CP pancreas exhibited a higher expression of Il1β, a proinflammatory factor associated with pancreatitis, suggesting that macrophages in the CP group exhibited M1-directed polarization." (PMID 35741777, 2022). "Moreover, pyroptosis promotes severe pancreatitis and associated lung injury through the release of cytokines IL-1β and IL-18, and is implicated in acute myocardial injury and spinal cord injury." (PMID 39717896, 2024). "Specifically, Zn sulfate supplementation in rats with pancreatitis significantly reduced endotoxic accumulation (LPS) and tissue IL-1β and TNFα expression, as well as attenuated pancreatitis-associated gut permeability and bacterial translocation to pancreas, liver, and mesenterial lymph nodes." (PMID 34884881, 2021). "Interestingly, lipotoxic severe pancreatitis is associated with increased IL-1β levels in both the necrotic collections and serum." (PMID 31963691, 2020). "Furthermore, TNF‐α, IL‐6 and IL‐1β expression has shown a close correlation with the infiltration of activated inflammatory cells into the pancreas and is also associated with the severity of pancreatitis." (PMID 27957800, 2017). "For example, hypoxic conditions often lead to the upregulation of interleukin-1β (IL-1β) and interleukin-6 (IL-6), contributing to the inflammatory environment characteristic of pancreatitis." (PMID 40787634, 2025). "Results indicated that IL-6, IL-18, and IL-1β were all significantly elevated in pancreatitis samples." (PMID 40787634, 2025). "TNF-α and IL-1β levels in the melatonin-treated pancreatitis group were significantly lower than in the pancreatitis group (P<0.05)." (PMID 38333760, 2024). "In the present study, TNF-α and IL-1β levels were significantly lower than those of the pancreatitis group as a result of pre-application of melatonin." (PMID 38333760, 2024). "TNF-α, IL-1β, and IL-10 levels increased significantly (P<0.05) in pancreatitis compared to the control group." (PMID 38333760, 2024). "Elevated IL-1β has been associated with pancreatitis, a recognized risk factor for PDA and high intratumoral and serum IL-1β has been associated with poorer overall survival and increased chemoresistance in PDA patients." (PMID 37081882, 2023). "Pretreatment with warfarin administered at doses of 90 or 180 μg/kg/dose significantly reduced the pancreatitis-evoked increase in the serum level of IL-1β (WF + CIAP and WF 180 + CIAP)." (PMID 37371528, 2023). "Development of pancreatitis is associated with strong up-regulation of inflammatory mediators such as tumor necrosis factor (TNF)α, Interleukin IL-1β, IL-6 and chemokines of the CXC and CC families." (PMID 37373094, 2023). "The administration of gs-4997 to mice with pancreatitis largely reduced the upregulation of IL-6, IL-1β, TNF-α, and MCP-1." (PMID 36316322, 2022). "Inflammatory cells are activated, exhibit direct cytotoxicity, or release pro-inflammatory cytokines such as IL-1β and IL-6, which are crucial in the beginning of a number of pathological processes in pancreatitis." (PMID 36232419, 2022). "The activation of NLRP3 inflammasome will deteriorate inflammation of pancreatitis, and esults in production of IL-1β, IL-18, and HMGB1, which are associated with systemic injury." (PMID 33967799, 2021). "Cytokine abnormalities, such as elevation of interleukin 1β (IL-1β), IL-6, IL-8, and IL-10, are involved in pancreatitis and IBD." (PMID 32831829, 2020). "Genetic deficiency of TLR9 alleviates pancreatic edema, inflammation, and pro-IL-1β expression in pancreatitis." (PMID 32076577, 2020). "Pro-inflammatory cytokines, such as TNF-α, IL-6, and IL-1β, that are released during the course of pancreatitis mediate the pathogenesis of SIRS including lung injury." (PMID 29847178, 2018).
pancreatitis (continued). "In pancreatitis, the inflammatory response is triggered by the production of a series of inflammatory cytokines such as IL-6, IL-1β, and TNF-α." (PMID 29849486, 2018). "The proinflammatory cytokines TNF-α and IL-1β are known to mediate amplification of inflammatory process during pancreatitis." (PMID 25214720, 2014). "Other studies showed that downregulation of NF-κB not only inhibited ICAM-1 and IL-1β expression, but also attenuated pancreatic and hepatic injury in pancreatitis." (PMID 22529518, 2012). "It has been suggested that pro-inflammatory cytokines, such as TNF-α and IL-1β are upregulated during pancreatitis." (PMID 27956946, 2009). "Plasma levels of pro-inflammatory cytokines (TNF-α, IL-1β) in the pancreatitis group were significantly higher (p < 0.001) than that of the control group, while treatment of proanthocyanidin abolished these elevations significantly (p < 0.01)." (PMID 27956946, 2009). "Emerging evidence underscores the pivotal role of interleukins (ILs) in pancreatitis pathogenesis across the disease spectrum, encompassing both pro-inflammatory mediators (e.g., IL-1β, IL-6, and IL-8) and anti-inflammatory regulators (e.g., IL-10 and IL-37) 24-26." (PMID 41208897, 2025). "IL-1β plays an important role in pancreatitis, as mice overexpressing IL-1β develop ADM." (PMID 37373094, 2023). "Furthermore, PARP inhibitors have demonstrated effects on reducing pro-inflammatory mediators in the plasma such as TNF-α, IL-1β, IL-2, IL-4, IL-6, IL-12, IP-10, and KC on in vitro models of pancreatitis as well as in vivo models of wound healing injuries." (PMID 33663560, 2021). "IL-6 levels which could be induced by TNFα and IL-1β, are elevated in pancreatitis and serve as markers of the severity of pancreatitis." (PMID 32587518, 2020). "IL-1β has also been shown to have an important role in the pathogenesis of pancreatitis." (PMID 22359633, 2012). "In the antisense treated rats with pancreatitis there was 3.5-fold greater serum amylase, increased tissue edema and histological inflammatory scores, and elevated levels of IL-1α, IL-1β, and IL-4 mRNAs in peripheral blood monocytes compared to rats treated with a sense oligonucleotide." (PMID 16700916, 2006). "In addition, serum activity of lipase and amylase, serum concentrations of interleukin-1β (IL-1β), and plasma D-dimer concentration were not affected by acenocoumarol given in rats without causing pancreatitis." (PMID 27754317, 2016). "In addition, acenocoumarol given at the dose of 50 or 100 μg/kg/dose significantly decreased the pancreatitis-evoked increase in pancreatic weight serum activity of lipase and amylase, and serum concentration of pro-inflammatory IL-1β." (PMID 27754317, 2016). "Indeed, we observed that induction of pancreatitis robustly increased plasma concentration of several inflammatory cytokines including IL1α (2.6-fold), IL1β (12.8-fold), VEGF (70.5-fold) TNFα (4.5-fold), and IL6 (585.2-fold) as well as stimulated p38 kinase activation in pancreatic tissue." (PMID 24480543, 2014). "The levels of inflammatory cytokines, especially proinflammatory cytokines such as IL-6, IL-1β and TNF-α, which are indicators of severity in pancreatitis, are also important." (PMID 38698325, 2024). "Immunofluorescence staining for cytokines and ST6GAL1 revealed that ST6GAL1 was co-expressed with IL-1β and IL-6 in the epithelial cells of PDAC and pancreatitis tissues." (PMID 39260693, 2024). "Compared with the normal pancreas, elevated levels of IL-1β and IL-6 were observed in the PDAC and pancreatitis specimens." (PMID 39260693, 2024). "In the progression of pancreatitis in mice, LMT-28 treatment also reduced the expression of the proinflammatory cytokines IL-1β and TNF-α." (PMID 36643585, 2023). "IL-1β, TNF-α, IL-6, IL-8, and IL-18 are widely reported pro-inflammatory cytokines that are key indicators for the early prediction and diagnosis of pancreatitis." (PMID 35663952, 2022).
pancreatitis (continued). "Subsequently, in the in vitro experiments, the AR42J and HPDE6-C7 pancreatitis models induced by caerulein confirmed that overexpression of SNHG11 can reduce the expression of inflammatory factors IL6, IL1-β, and TNF-alfa." (PMID 36611865, 2022). "Therefore, we surmise that TMAO causes the expression of the proinflammatory factors IL-1β, IL-6, and TNF-α to increase significantly by activating the p65 NF-κB pathway, which increases the level of Ca2+ in pancreatic acinar cells, inducing a sensitive state of pancreatitis." (PMID 34925503, 2021). "During pancreatitis, serum amylase, lipase and cytokine, such as IL6, IL-1β and TNF-α, levels are increased." (PMID 32842687, 2020). "In the present pancreatitis study, RAI with ATL significantly decreased the content of pro-inflammatory cytokines, such as TNF-α, IL-1β and IL-6." (PMID 25265022, 2014). "The present paper suggests that treatment of zerumbone on rat attenuates the severity of acute necrotizing pancreatitis and pancreatitis-induced hepatic injury, via inhibiting NF-κB activation and downregulating the expression of ICAM-1 and IL-1β." (PMID 22529518, 2012). "However, pancreatitis or local pancreatic injury can induce the release of a plethora of inflammatory factors such as TNF-α and IL-1β, thereby triggering activation of the caspase-3 pathway and subsequent apoptosis of intestinal mucosal epithelial cells." (PMID 39450142, 2024). "Although we did not investigate the specific role of IL11 in the immune response in pancreatitis, we found that blocking IL11 signalling had anti-inflammatory effects and reduced IL6, IL1β and TNFα protein levels as well as diminishing NF-κB and STAT3 activation." (PMID 35408908, 2022). "Therefore, the levels of IL-6, IL-1β, and TNF-α in LPS-induced pancreatitis model in vitro were detected." (PMID 33824873, 2021). "Therefore, after GQD intervention, the production of NLRP3 can be inhibited, thereby reducing the synthesis of Caspase-1 and GSDMD, lowering the release of inflammatory factors such as IL-1β and IL-18, and increasing IL-10 levels, thereby preventing the progression of post ERCP pancreatitis." (PMID 40620677, 2025). "Moreover, emodin could notably decrease the release of pancreatitis markers (amylase and lipase) and inflammatory mediators, such as TNF-α, IL-1β, and IL-6." (PMID 29163548, 2017). "Moreover, the levels of Th1 inflammatory mediators including IL-6, IL-1β, IFN-γ, and TNF-α decreased in pancreatic tissue after fucoidan intervention, indicating that fucoidan could relieve Th1 cells and Th1 cytokine-mediated pancreatitis locally." (PMID 38164477, 2024). "The administration of 90 μg/kg G-CSF 1 hour before the induction of pancreatitis in rats increased the number of peritoneal-exudate neutrophils and circulating neutrophils without increasing the concentration of TNF-α, IL-6, and IL-1β." (PMID 25551560, 2014).